NLRP3 (NLR family pyrin domain containing 3)
Diseases named in the same sentence as NLRP3 in open-access papers (continued):
Sharing a sentence is not in itself a finding about the gene and the disease.
Obesity (continued). "Thioredoxin-interacting protein (TXNIP) is elevated in diabetes and obesity and has been linked to NLRP3 inflammasome activation." (PMID 36670488, 2023). "Significant improvement in atrial fibrosis and reduction in susceptibility to AF induced by obesity-related gut ecological dysregulation through inhibition of ferritin excess or NLRP3 inflammasome signaling pathways." (PMID 38077349, 2023). "Our results on obesity and NLRP3 are in agreement with a previous systematic review published in 2017 by Rheinheimer and co-workers who reported that obesity is associated with increased adipose tissue NLRP3 expression levels." (PMID 37446154, 2023). "The activation of NLRP3 has also been linked to various metabolic and inflammatory conditions such as gout, diabetes, insulin resistance, and obesity." (PMID 37251328, 2023). "Since nutrient excess generates DAMPs, NLRP3 activation has been linked to chronic inflammation in obesity and IR." (PMID 37599368, 2023). "Of the 22 human NLRs known to date, six proteins (NLRP3, NLRP6, NOD1, NOD2, NLRC5 and NLRP12) have been described to be associated with obesity and low-grade inflammation and one (NLRP3) with postprandial inflammation." (PMID 37239938, 2023). "Meanwhile, NLRP3 exerts a predominant role in the pathogenesis of obesity-associated inflammatory diseases." (PMID 36922854, 2023). "NLRP3 activation can induce pyroptosis through caspase‐1 and then promote myocardial dysfunction progression, and obesity‐associated protein inhibits NLRP3‐mediated pyroptosis to attenuate myocardial ischemia–reperfusion injury." (PMID 37724419, 2023). "In line with this concept, obesity-induced insulin resistance is alleviated in mice genetically deficient in NLRP3." (PMID 36670488, 2023). "NLRP3 deficiency attenuated obesity-induced SC damage and BTB impairment, improving testosterone secretion by Leydig cells and sperm quality." (PMID 35915511, 2022). "Saroglitazar ameliorated obesity and associated inflammation via modulation of NLRP3 inflammasome and NF- κB in MSG obese Wistar rats." (PMID 36033946, 2022). "Chronic conditions of inflammation, often seen with advancing age, and in co-morbidities including hypertension, coronary artery disease and obesity, are all risk factors for the onset of kidney disease, where NLRP3 activation is pivotal to pathology." (PMID 35755447, 2022). "NLRP3-deficient mice were fed a high-fat diet for 24 weeks to establish obesity-related spermatogenesis impairment." (PMID 35915511, 2022). "DCA can stimulate the expression of S1PR2, regulate the protein kinase (ERK) signali pathway, and induce the activation of NLRP3 inflammasomes, which is one of the causes of chronic inflammation caused by obesity." (PMID 35845812, 2022). "We summarize the current studies and potential mechanisms associated with autophagy and NLRP3 inflammasome in AT inflammation and aim to provide further evidence for research on obesity and obesity-related complications." (PMID 35432210, 2022). "Inappropriate NLRP3 inflammasome activation is implicated in the pathogenesis of a variety of CID including obesity and cancer." (PMID 36555392, 2022). "The NLRP3 inflammasome has been implicated in various obesity-related pathologies, including AF, and has been shown to be inhibited by pharmacologic SGK1 inhibition." (PMID 35998035, 2022). "To summarize, these findings strongly support the idea that the “inflammasome NLRP3” detects danger signals caused by obesity, resulting in increased inflammation and organ failure." (PMID 35456284, 2022). "Murine studies showed that genetic deficiency for NLRP3 protects mice against high fat diet-induced obesity and insulin resistance, while NLRP3 knockdown reduces AT inflammation and extracellular matrix remodelling in AT samples from people with obesity." (PMID 35931812, 2022). "The “metabolic syndrome” diseases type 2 diabetes and obesity, due to their chronic inflammatory nature, are associated with NLRP3 inflammasome activation." (PMID 34202842, 2021).
Obesity (continued). "Second, the NLRP3 inflammasome has been suggested to affect the regulation of adiposity and insulin sensitivity in the course of obesity, and mice deficient in NLRP3 were reported to be resistant to the development of obesity induced by a high-fat diet (HFD)." (PMID 35046893, 2021). "NLRP3 activity has been extensively implicated in the pathophysiology of several metabolic disorders including obesity, type 2 diabetes, gout, and CVD, all of which occur more frequently in BD." (PMID 34112182, 2021). "The NLRP3 inflammasome directs the obesity-associated danger signal, giving rise to obesity-induced inflammation and insulin resistance." (PMID 33803178, 2021). "Systemic inflammation is a common characteristic linking obesity, metabolic syndrome and elevated cardiovascular risk, 22 with highlighted role for IL-1β and NLRP3 inflammasome." (PMID 33542047, 2021). "Many studies have found that NLRP3 inflammasomes correlated with pyroptosis participate in the pathogenic mechanism of some metabolic diseases, including obesity and type 2 diabetes mellitus." (PMID 34737754, 2021). "The activation of the recombinant NLR family, pyrin domain containing protein 3 (NLRP3) inflammasome by damage-associated molecular patterns (DAMPs), such as dietary free fatty acids (FFAs), is a key event in obesity-induced inflammation." (PMID 34107901, 2021). "The deletion of NLRP3 or inhibition of caspase-1 in mice resulted in improved insulin sensitivity and ameliorated obesity-associated pathologies." (PMID 34070553, 2021). "It has been reported that NLRP3 inflammasome perceives obesity related risk signals and participate in inflammation and insulin resistance caused by obesity." (PMID 33796528, 2021). "Nevertheless, inhibition of NLRP3 in a mouse model protects against obesity-induced inflammasome activation in the fat-associated pits and liver, and improves insulin signaling." (PMID 33803178, 2021). "Collectively, human studies indicate that insulin resistance and obesity are strongly associated with increased NLRP3 expression in adipose tissue." (PMID 33546399, 2021). "Noteworthy, failure in ovarian leptin signaling in late obesity was associated with the repression in NLRP3 activity, but with maintenance of inflammation and levels of IL-1β." (PMID 34805147, 2021). "Several studies linked increased NLRP3 expression in adipose tissue and monocytes to obesity and T2D, respectively." (PMID 33178196, 2020). "The deletion of NLRP3 or inhibition of caspase-1 in mice was shown to improve insulin sensitivity and ameliorate obesity-associated pathologies." (PMID 32751530, 2020). "NLR family pyrin domain containing 3 (NLRP3) inflammasome plays a crucial role in adipose tissues in obesity-associated inflammatory response." (PMID 33126679, 2020). "Saturated fatty acids and ceramide, associated with obesity and nutrient overload, can also trigger NLRP3 inflammasome to produce IL-1β that acts on the liver and impairs the activity of liver insulin, contributing to insulin resistance." (PMID 33113859, 2020). "Among them, the NLR family pyrin domain containing 3 (NLRP3) inflammasome was associated with obesity and IR." (PMID 33138337, 2020). "Obesity, T2D, and AD are affected by the involvement of NLRP3; here, we focus on their association with each other from a therapeutic point of view." (PMID 32012695, 2020). "This phenotype was further exaggerated in the context of obesity, where cholangitis induced in NLRP3-deficient obese mice resulted in further exacerbated histopathology and increased levels of IL-13 and TNFα, suggesting a diet-specific profile." (PMID 32716024, 2020). "On the other hand, NLRP3 inflammasome is a determining marker of obesity-associated inflammation, and is also associated with autophagy, as it is well reported that autophagy (principally mitophagy) controls NLRP3 levels." (PMID 33114725, 2020).
Obesity (continued). "Obesity and specifically obesity-associated insulin resistance have been linked to the activity of the NLRP3 inflammasome." (PMID 32751530, 2020). "Nonetheless, the detailed mechanism of inflammasome activation that leads to obesity and causes T2D as well as treatment modalities based on NLRP3 inhibition remains to be explored." (PMID 32012695, 2020). "Activation of the NLRP3 inflammasome has been implicated in insulin resistance and associated diseases, such as Alzheimer’s disease, obesity, and cardiovascular disease." (PMID 32085388, 2020). "Activation of the NOD-like receptor pyrin-domain containing 3 (NLRP3) inflammasome is associated with chronic low-grade inflammation in metabolic diseases such as obesity." (PMID 32209983, 2020). "We have previously reported that NLRP3 deficiency had a beneficial effect on obesity-induced myocardial remodeling and dysfunction in mice." (PMID 33273482, 2020). "FABP4, an adipokine that is positively associated with obesity and metabolic syndrome, was demonstrated to positively control the NLRP3 inflammasome through downregulating UCP2 expression in a paracrine manner." (PMID 32545355, 2020). "A study performed in the high-fat fed model of obesity-related type 2 DM demonstrated an association between inflammasome activation, attested by NLRP3 upregulation and increased levels of cleaved IL-1β and caspase-1, and retinal dysfunction." (PMID 32751658, 2020). "Mice deficient for NLRP3 are protected from diet-induced insulin resistance due to failure to form the inflammasome complex; similarly, therapeutic intervention for weight loss in obesity and T2D reduces expression of NLRP3 and its target cytokines." (PMID 32785109, 2020). "Herein, we examined the effect of long-term HFD consumption on obesity associated cardiac remodeling in NLRP3 and ASC (Pycard) deficient mice." (PMID 31379826, 2019). "The NLRP3 inflammasome and downstream activity have been associated with both asthma and obesity in humans." (PMID 30791383, 2019). "Consistent with previous studies, some researchers provided direct in vivo evidence that activation of the NLRP3 inflammasome in diet-induced obesity is essential for causing pancreatic damage." (PMID 31174550, 2019). "NLRP3 inflammasome is considered to have a critical role in sensing obesity-associated metabolic stress and mediating the associated inflammatory response and insulin resistance development." (PMID 31379826, 2019). "In the mouse model, IL-17, IL-1β and the NLRP3 inflammasome have been implicated in the pathogenesis of obesity-induced airway hyperresponsiveness." (PMID 30670753, 2019). "Murine and human models revealed that increased NLRP3 expression in adipose tissue is linked to obesity-associated insulin resistance." (PMID 31998283, 2019). "The NLRP3 inflammasome has been associated with obesity-induced insulin resistance and pancreas beta cell failure." (PMID 31174550, 2019). "Subsequent evidence suggests that NLRP3 inflammasome activation can increase the susceptibility of several diseases, including obesity, insulin resistance, T2DM, and some autoimmune disorders." (PMID 29497383, 2018). "Further studies are required to fully explain the molecular pathways underlying the impact of NLRP3-IL-1β in obesity-associated CRC." (PMID 30619282, 2018). "The future study measuring the vascular reactivity using the inhibitors of NLRP3 and caspase‐1 can determine the direct roles of inflammasome in obesity‐associated vascular dysfunction and the impact of physical activity." (PMID 29932503, 2018). "Other research has shown that obesity was associated with the activation of the NLRP3 in adipose tissues." (PMID 29686666, 2018). "They concluded that overall human studies indicate that obesity and insulin resistance are associated with increased NLRP3 expression in adipose tissue and studies in obese mice corroborate this association." (PMID 29538286, 2018).
Obesity (continued). "Considering that the development of obesity is associated with hypoxia and adipocyte death, NLRP3 is preferentially expressed in ATMs from the crown-like structures." (PMID 30619282, 2018). "T cells in obese AT are regulated by NLRP3 inflammasome, which senses obesity-associated danger signals and contributes to obesity-induced inflammation and insulin resistance." (PMID 28838042, 2017). "Surplus levels in nutrients associated with caloric overload as well as low-level of circulatory endotoxemia (LPS), as in the case of obesity, cause NLRP3 activation playing an important role in the perpetuation of insulin resistance and inflammation." (PMID 28335527, 2017). "The NLRP3 inflammasome plays a substantial role in sensing obesity-associated inducers of caspase-1 activation and therefore regulates the magnitude of inflammation." (PMID 27686325, 2016). "The findings for the first time demonstrate the critical role of Asm in the activation of Nlrp3 inflammasomes and subsequent glomerular dysfunction or sclerosis associated with obesity." (PMID 26980705, 2016). "Nlrp3 was further implicated in causing obesity-induced pancreatic damage in a mouse model of obesity." (PMID 27128935, 2016). "The NLRP3 inflammasome thus conceptually provides an attractive target in the control of obesity-associated chronic inflammation." (PMID 27803798, 2016). "Our results demonstrate that Asm gene deficiency in the kidney attenuates the obesity-induced Nlrp3 inflammasome formation, activation and glomerular injury, ultimately preventing glomerulosclerosis." (PMID 26980705, 2016). "Nlrp3 also had roles in causing islet fibrosis and β-cell death, common occurrences in obesity-induced pancreatic damage." (PMID 27128935, 2016). "The present study was designed to explore the role of acid sphingomyelinase (Asm), a ceramide producing enzyme in obesity-induced NLRP3 inflammasome activation and associated glomerular injury." (PMID 26980705, 2016). "NLRP3 inflammasome is implicated in diseases, such as Alzheimer’s disese, obesity, major depressive disorder, obesity induced type 2 diabetes, and fibromyalgia." (PMID 25867480, 2015). "The role of the NLRP3 inflammasome in the pathogenesis of obesity-induced insulin resistance is derived from observations that NLRP3 deficient mice fed a high fat diet are more insulin sensitive than HF-diet fed wild-type mice." (PMID 26437377, 2015). "With the NLRP3 inflammasome serving as a sensor of obesity-associated danger signals, the progression of obesity can switch macrophages from “M2-like” to “M1-like” cells." (PMID 25506346, 2014). "The association between the NLRP3 inflammasome and both insulin resistance and obesity has been suggested by animal studies showing that genetic ablation of NLRP3 improved insulin sensitivity and glucose homeostasis." (PMID 23843683, 2013). "The NLRP3 inflammasome appears to be an important sensor of metabolic dysregulation and controls obesity-associated insulin resistance and pancreatic beta cell dysfunction." (PMID 23483669, 2013). "The NLRP3 inflammasome instigates inflammation and causes leukocytosis (i.e., increased immune cell infiltration) in visceral adipose tissue during obesity." (PMID 23483669, 2013). "NLRP3 inflammasome plays a substantial role in sensing obesity-associated inducers of caspase-1 activation and therefore regulates the magnitude of the inflammation and its downstream effects on insulin signaling in different organs, as reported here later." (PMID 23843683, 2013). "It has been reported that PA induced the activation of the NLRP3 inflammasome which then senses obesity-associated danger signals and contributes to obesity-induced inflammation." (PMID 22515414, 2012). "Furthermore, HSR failure in obesity is linked to increased low-grade inflammation, including activation of JNKs and NLRP3 inflammasome persistence, where HSP70 serves as a negative regulator of both JNKs and NLRP3 inflammasome activation." (PMID 39716481, 2025).
Obesity (continued). "As such, the targeted inhibition of NLRP3 may represent a promising therapeutic strategy to attenuate AF risk in the context of obesity." (PMID 40649732, 2025). "In a translational study encompassing obese mice, sheep, and human subjects, obesity was consistently associated with heightened activation of the NLRP3 inflammasome across all three species, implicating a conserved inflammatory axis in obesity-induced atrial remodeling." (PMID 40649732, 2025). "NLRP3 is a key component of the innate immune system and forms part of the inflammasome that has been implicated in chronic low-grade inflammation associated with metabolic syndrome, including obesity, insulin resistance, and type 2 diabetes." (PMID 40869066, 2025). "Moreover, NLRP3 activation is closely associated with obesity‐related inflammation, insulin resistance, and type 2 diabetes." (PMID 40589337, 2025). "Notably, these pathological alterations were mitigated in NLRP3−/− mice, establishing a causal role for NLRP3 inflammasome activation in obesity-induced AF." (PMID 40649732, 2025). "Since uncontrolled inflammation and aberrant activation of the NLRP3 inflammasome are associated with the development of inflammatory diseases linked to obesity, aging, and infections, EOC shows promise as a natural agent for promoting health and preventing such conditions in the future." (PMID 40508226, 2025). "However, the role of enteric glial NLRP3 inflammasome in the pathogenesis of intestinal mucosal barrier alterations associated with obesity remain still unclear." (PMID 39287080, 2025). "Pathways beyond NLRP3 inflammasome activation may contribute to IL-18 production, which has also been directly linked to obesity in previous studies." (PMID 40004007, 2025). "Studies have suggested that the NLRP3 inflammasome may be linked to the low-grade chronic inflammation associated with obesity and the development of CRC 66-68." (PMID 40520898, 2025). "We here sought to determine whether NLRP3 inflammasome inhibition could ameliorate obesity cardiomyopathy and if so, to further explore its underlying mechanisms." (PMID 39604027, 2024). "Interestingly, NT-0249, a brain-penetrant NLRP3 inhibitor, induced weight loss in obese mice comparable to that caused by semaglutide, an anti-diabetic drug that is also used to treat obesity." (PMID 39301197, 2024). "Notably, the increasing expression of the NLRP3 inflammasome is a predominant factor in the pathogenesis of obesity-associated adipose tissue inflammation." (PMID 39201638, 2024). "Impeding NLRP3 inflammasome may be a potent therapeutic strategy for obesity‐associated cardiomyopathy." (PMID 39604027, 2024). "Furthermore, we uncovered a distinct molecular mechanism underlying the anti-obesity effects associated with the hepatic NLR family pyrin domain-containing 3 (NLRP3) inflammasome and autophagic clearance by the vera@CLCMP hydrogel patches." (PMID 36670488, 2023). "However, it should be noted that we did not investigate adipose tissue T-cells, which have been previously implicated in obesity-related NLRP3 regulation." (PMID 38062308, 2023). "Mice deficient in NLRP3 are protected from fat diet-induced obesity and insulin resistance." (PMID 37372020, 2023). "In this context, the NLRP3 inflammasome can be activated by cholesterol crystals and ceramides due to the exacerbation of lipolysis in obesity, but can also be activated by bacteria, fungi, and viruses; however, NLRP3 is associated with metabolic and inflammatory conditions such as obesity." (PMID 36674982, 2023). "Furthermore, NLRP3 expression enhanced obesity-associated spermatogenic impairment and male infertility." (PMID 36671008, 2023). "Given that SPARC is a secreted protein, future studies to neutralize this matrikine through specific monoclonal antibodies may offer potential approaches to target NLRP3-driven inflammation and obesity-associated diseases." (PMID 37781916, 2023).